SRSF2 (serine and arginine rich splicing factor 2)
Description:
Necessary for the splicing of pre-mRNA. It is required for formation of the earliest ATP-dependent splicing complex and interacts with spliceosomal components bound to both the 5'- and 3'-splice sites during spliceosome assembly. It also is required for ATP-dependent interactions of both U1 and U2 snRNPs with pre-mRNA. Interacts with other spliceosomal components, via the RS domains, to form a bridge between the 5'- and 3'-splice site binding components, U1 snRNP and U2AF. Binds to purine-rich RNA sequences, either 5'-AGSAGAGTA-3' (S=C or G) or 5'-GTTCGAGTA-3'. Can bind to beta-globin mRNA and commit it to the splicing pathway. The phosphorylated form (by SRPK2) is required for cellular apoptosis in response to cisplatin treatment.
Synonyms: SC-35; SFRS2; SC35; PR264; SFRS2A; SRp30b
Tractability: PROTAC: ubiquitination databases record sites on it; its protein half-life has been measured.
Gene: Protein-coding gene on chromosome 17 (76,734,115 to 76,737,395, reverse strand). Ensembl gene ENSG00000161547.
Subcellular location: Nucleus; Nucleus, nucleoplasm; Nucleus speckle
Subcellular location (Human Protein Atlas): Nucleoplasm; Cytosol
Pathways (Reactome):
Metabolism of RNA: Processing of Capped Intron-Containing Pre-mRNA; Transport of Mature mRNA derived from an Intron-Containing Transcript; mRNA 3'-end processing; mRNA Polyadenylation; mRNA Splicing - Major Pathway; mRNA Splicing - Minor Pathway
Disease: Dengue Virus-Host Interactions
Gene Ontology:
Molecular function: protein binding; RNA binding; transcription corepressor activity; nucleic acid binding; pre-mRNA binding; protein kinase C binding
Biological process: mRNA processing; regulation of alternative mRNA splicing, via spliceosome; RNA splicing; negative regulation of DNA-templated transcription; response to vitamin E
Cellular component: nuclear speck; nucleoplasm; nucleus; PML body; interchromatin granule; perichromatin fibrils; spliceosomal complex
Genetic constraint (gnomAD): Loss-of-function variants: 1 observed, 9.1 expected, observed/expected ratio (o/e) 0.11, 90% interval 0.038 to 0.52. That is too few expected variants to judge how well the gene tolerates losing a copy. Missense variants: 62 observed, 215.97 expected, observed/expected ratio (o/e) 0.29, 90% interval 0.23 to 0.35. Synonymous variants: 127 observed, 91.7 expected, observed/expected ratio (o/e) 1.38, 90% interval 1.2 to 1.61.
Cancer hallmarks: escaping programmed cell death (suppresses); suppression of growth (promotes); escaping programmed cell death (promotes); tumour promoting inflammation; genome instability and mutations (suppresses); tumour promoting inflammation (suppresses); angiogenesis (suppresses); escaping immune response to cancer (promotes); invasion and metastasis (suppresses); proliferative signalling (promotes)
Homologues: Orthologues: chimpanzee SRSF2 (100% identical), dog SRSF2 (100% identical), macaque SRSF2 (100% identical), mouse Srsf2 (100% identical), rat Srsf2 (100% identical), pig SRSF2 (99% identical), tropical clawed frog srsf2 (93% identical), zebrafish srsf2a (83% identical), zebrafish srsf2b (80% identical), Drosophila melanogaster SC35 (50% identical), Caenorhabditis elegans rsp-4 (50% identical). Paralogues in human: SRSF8 (74% identical), SRSF10 (47% identical), SRSF12 (42% identical).
Diseases named in the same sentence as SRSF2 in open-access papers:
SRSF2 is named in the same sentence as 136 diseases in open-access papers, as found by Europe PMC text mining. Sharing a sentence is not in itself a finding about the gene and the disease. The quoted sentences say what the papers report.
myelodysplastic syndrome (80 papers, 2013 to 2026). A clonal hematopoietic disorder characterized by dysplasia and ineffective hematopoiesis in one or more of the hematopoietic cell lines. "They demonstrated that SRSF2 mutations, which are usually heterozygous in human myelodysplastic neoplasms (MDS) and AML, depend on the wildtype allele for survival in mouse models of both diseases." (PMID 40140631, 2025). "TET2, ASXL1, DNMT3A, and SF3B1 are all known to harbor causal leukemia variants, and somatic variants in SRSF2 have been described in myelodysplastic syndrome." (PMID 39132489, 2024). "Patients with myelodysplastic syndrome (MDS) have been found to contain SRSF2 mutations, particularly the p95 mutation, which is associated with lower survival rates in MDS patients." (PMID 39584923, 2024). "Oncogenic mutations in the splicing factor SRSF2 activate a mitochondrial surveillance mechanism, providing a therapeutic vulnerability in SRSF2-mutant acute myeloid leukemia and myelodysplastic syndrome." (PMID 38713535, 2024). "Mutations in splicing factors U2AF1 and SRSF2, which are associated with myelodysplastic syndrome (MDS), have been linked to R-loops and have functional incapacitation variants in SF3B1 in a zebrafish model." (PMID 37894353, 2023). "In fact, mutations in U2AF1, SF3B1, and SRSF2 genes are frequently found in patients affected by myelodysplastic syndromes (MDSs), which are myeloid cancers typical of the elderly." (PMID 38132139, 2023). "Heterozygous mutations in SRSF2 occur in patients with myelodysplastic syndromes, chronic myelomonocytic leukemia, and myeloproliferative neoplasm, which are related to poor prognosis." (PMID 36623729, 2023). "Recurrent mutations in SRSF2 globally affected the RNA binding and splicing process, such as the hnRNP family of protein, resulting in poor clinical outcomes in myelodysplastic syndromes." (PMID 33749163, 2021). "The frequency and pattern of mutation in SF3B1 and SRSF2 RNA splicing machinery genes were found to vary among myelodysplastic syndrome (MDS) patients in different populations." (PMID 31030497, 2019). "Mutations in the human SRSF2 gene altering its RNA-binding affinity impairs hematopoietic differentiation in vivo and is frequently (40% incidence) found in patients with myelodysplastic syndromes and certain leukaemias." (PMID 31186410, 2019). "Altered or loss of function of splicing factors such as U2AF1, hnRNPA1, SF3B1, and SRSF2 results in profound deficiencies in hematopoiesis and myelodysplastic syndromes." (PMID 29875770, 2018). "It has been recently discovered that SRSF2, along with other splicing regulators, is frequently mutated in patients with myelodysplastic syndrome (MDS)." (PMID 27552991, 2016). "For example, genes that encode U2AF, SF3B1 and SRSF2 are mutated in myelodysplastic syndromes, while others promote cancer or provide a cancer-specific metabolic signature." (PMID 26529031, 2015). "By contrast, mutations affecting spliceosome genes SF3B1 and SRSF2, closely associated with the myelodysplastic syndromes, were identified only in those aged >70 years, with several individuals harboring more than one such mutation." (PMID 25732814, 2015). "Hotspot mutations of serine/arginine-rich splicing factor 2 (SRSF2) gene have been identified in a proportion of hematologic malignancies including myelodysplastic syndrome (MDS)." (PMID 25541999, 2014). "Even in hematopoietic tumor diseases such as myelodysplastic syndromes and acute myeloid leukemia, an association with SRSF2 mutations has been observed, e.g., in correlation with malignant transformation, reduced overall survival, and increased therapy resistance." (PMID 41228255, 2025). "Moreover, previous studies showed the frequent mutations on P95 proline residue in SRSF2 occur in patients with myelodysplastic syndromes." (PMID 36623729, 2023).
myelodysplastic syndrome (continued). "Interestingly, a mutation in SRSF2 (SRSF2P95H) associated with myelodysplastic syndromes skews the binding specificity of SRSF2 from GGNG towards CCNG, affecting its binding to exons but not the global alternative splicing pattern." (PMID 34940860, 2022). "Mutations in U2AF1 and SRSF2 affect the spliceosome and are frequently found in antecedent hematological disorders, such as myelodysplastic syndrome (MDS) and myeloproliferative neoplasms (MPN), as well as are mutations in chromatin regulating genes ASXL1 and BCOR." (PMID 33509276, 2021). "SRSF2 mutations occur frequently in patients with myelodysplastic syndromes (MDS)." (PMID 31295920, 2019). "Of note, SRSF2 was linked with poor survival of patients with myelodysplastic syndromes and the frequent mutation of SRSF2 could induce oncogenesis in hematopoietic cells through activating a cascade of alternative splicing." (PMID 30640723, 2019). "Recent whole-genome-wide sequencing studies of patient samples with myelodysplastic syndromes have revealed frequent somatic mutations in a key group of spliceosome-associated proteins, including Serine/arginine-rich splicing factor 2 (SRSF2) and Splicing factor U2AF 35 kDa subunit." (PMID 31315652, 2019). "The mechanism of CDC25C alternative splicing and its downstream effects may be pertinent to the role of SRSF2′s point mutation in the development of myelodysplastic syndrome." (PMID 27552991, 2016). "A heterozygous hotspot mutation in SRSF2 gene has been identified in hematologic malignancies with varying frequencies, including myelodysplastic syndrome (MDS), acute myeloid leukemia (AML), chronic myelomonocytic leukemia (CMML), primary myelofibrosis (PMF), and systematic mastocytosis." (PMID 25541999, 2014). "Recurrent mutations in SR proteins are rarely identified, except for SRSF2 in hematologic malignancies, including myelodysplastic syndromes (MDS) and leukemia." (PMID 36833284, 2023). "SRSF2 mutations involving proline 95 residue (SRSF2P95) have been found in patients with various myeloid neoplasms including myelodysplastic syndromes (MDS), chronic myelomonocytic leukemia (CMML), MPN and acute myeloid leukemia (AML)." (PMID 38012156, 2023). "SRSF2/TET2 are commonly co-mutated in myelodysplastic syndromes (MDS) characterized by myelodysplasia and monocytosis." (PMID 33436578, 2021). "Mutations in SRSF2 gene are frequently reported in myelodysplastic syndromes (MDS) and acute myeloid leukemia (AML)." (PMID 31040863, 2019). "High‐frequency mutations of SF3B1 or SRSF2 have been described in patients with myelodysplastic syndromes (MDS), chronic myelomonocytic leukemia, and acute myeloid leukemia (AML)." (PMID 29769258, 2018). "It was recently discovered that SRSF2 is mutated in 10−15 % of patients with Myelodysplastic syndrome (MDS) and 25–30 % of patients with chronic myelomonocytic leukemia (CMML)." (PMID 27552991, 2016). "Spliceosome mutations, such as those in SF3B1, SRSF2, U2AF1, and ZRSR2, are commonly found in myeloid neoplasms like myelodysplastic syndromes (MDSs) and other MPNs." (PMID 40507313, 2025). "Recurrent somatic mutations in the spliceosome genes SF3B1, SRSF2, and U2AF1 are frequently identified in patients with myeloid neoplasms, such as myelodysplastic syndromes." (PMID 40386435, 2025). "In myelodysplastic syndromes (MDS), mutations in the SRSF2 induce aberrant recognition of specific exons, generating splice isoforms containing PTCs." (PMID 40563429, 2025). "SRSF2 mutant myelodysplastic syndrome (MDS) is catheterised by high GMP content and high levels of senescence and immunosenescence." (PMID 39235452, 2024). "In hematological tumors, more than half of patients with myelodysplastic syndromes (MDS) show mutations in functional components of the spliceosome, commonly in serine-rich SFs, such as SF3B1, SRSF2, and U2AF1." (PMID 36611187, 2023).
myelodysplastic syndrome (continued). "For example, mutation of SRSF2 alters its RNA-binding recognition and thereby promotes mis-splicing and NMD of EZH2, results in impaired hematopoietic differentiation in myelodysplastic syndromes (MDS) development." (PMID 35379802, 2022). "Previous studies have demonstrated that the SRSF2 mutant is associated with myelodysplastic syndromes (MDS), since the mutated SRSF2 expression alters the binding specificity, inducing the inclusion of a premature termination codon (PTC)." (PMID 35327956, 2022). "Mutations in key factors of the spliceosome, such as SRSF2, SF3B1, U2AF1, and ZRSR2, occur in a large fraction of myelodysplastic syndromes." (PMID 34858828, 2021). "Genes of the spliceosome-complex including SRSF2, SF3B1, U2AF1, and ZRSR2 are frequently mutated in myeloid malignancies such as AML, myelodysplastic syndromes (MDS) or myeloproliferative disorders." (PMID 33692956, 2021). "Recurrent, heterozygous and mutually exclusive mutations of splicing factors SF3B1, SRSF2 and U2AF1 frequently occur in blood and solid cancers (for instance in myelodysplastic syndromes, chronic lymphocytic leukaemia, acute myeloid leukaemia, uveal melanoma and breast cancer)." (PMID 36855776, 2023). "CMML is characterized by sustained monocytosis and an overlap of myeloproliferative neoplasms (MPN) and myelodysplastic syndromes (MDS) resulting from a cumulative mutational landscape including TET2 (60%), SRSF2 (50%), ASXL1 (40%), and the oncogenic RAS pathway (30%) mutations." (PMID 35884612, 2022). "Mutational profiles of myelodysplastic syndromes (MDS) have established that a relatively small number of genetic aberrations, including SF3B1 and SRSF2 spliceosome mutations, lead to specific phenotypes and prognostic subgrouping." (PMID 39235452, 2024). "The frequency of SRSF2 mutation in AML patients is approximately 10%, whereas in myelodysplastic syndrome (MDS) patients it ranges from 20% to 30%, and it is approximately 50% in patients with CMML." (PMID 39584923, 2024). "Recurrent somatic mutations of the SFG, such as SF3B1, SRSF2, U2AF1, and ZRSR2, have been uncovered in myelodysplastic syndrome (MDS), chronic lymphocytic leukemia, acute myeloid leukemia, breast cancer, lung adenocarcinoma, and uveal melanoma." (PMID 36684432, 2022). "Splicing of mRNA (e.g., in SF3B1, SRSF2) also occurred in haematological tumours such as myelodysplastic syndrome (MDS) and chronic lymphocytic leukaemia (CLL) resulting in resistance to treatment." (PMID 33670515, 2021). "Among these factors, SF3B1, SRSF2, and U2AF1, are most frequently mutated in patients with myelodysplastic syndrome (MDS), and also commonly occurred in clonal hematopoiesis, acute myeloid leukemia (AML), CLL, and a variety of solid tumors." (PMID 32481522, 2020). "Studies have shown that in myelodysplastic syndrome (MDS) SRSF2 was mutated in 12–14% of the cases and mutations in U2AF1 occur in 15% of the MDS cases." (PMID 31426461, 2019). "SRSF2 is most commonly mutated in chronic myelomonocytic leukemia (CMML) (47%) and myelodysplastic syndromes (MDS) (15%)." (PMID 31330784, 2019). "Recently SRSF2 was found to be one of the major responsible genes of myelodysplastic syndrome (MDS)." (PMID 31040863, 2019). "Similarly, mutations in splicing regulators such as serine/arginine-rich splicing factor 2 (SRSF2) drive hematological malignancies, including myelodysplastic syndrome (MDS)." (PMID 41219960, 2025). "Mutations in RNA splicing factor genes including SF3B1, U2AF1, SRSF2, and ZRSR2 have been reported to contribute to development of myeloid neoplasms including myelodysplastic syndrome (MDS) and secondary acute myeloid leukemia (sAML)." (PMID 38883705, 2024).
myelodysplastic syndrome (continued). "Significant sex differences exist in the genomic aberrations underlying disease pathology, including a higher prevalence of SF3B1, SRSF2, and ASXL1 mutations in males and DNMT3A mutations in females with clonal hematopoiesis indeterminate potential and myelodysplastic syndromes (MDS)." (PMID 39402216, 2024). "SRSF2 mutations are the most common splicing machinery mutations (SMMs) identified in various myeloid malignancies (acute myeloid leukemia [AML], myelodysplastic syndrome [MDS], chronic myelomonocytic leukemia [CMML], and myeloproliferative neoplasms [MPNs])." (PMID 38558935, 2024). "In Myelodysplastic Syndromes (MDS), caused by splicing factor mutations in components such as SRSF2 and U2AF1, aberrant R-loop accumulation is linked to the compromised proliferation of bone-marrow-derived blood progenitors, a characteristic feature of MDS." (PMID 36553448, 2022). "SRSF2 P95H expression in mouse models leads to myeloid bias, impaired B cell development and maturation, and decreased haemopoietic stem cell numbers reminiscent of human myelodysplastic syndrome (MDS) in vivo." (PMID 32823933, 2020). "Moreover, hotspot mutations in the SRSF2 gene, such as P95H, change the binding properties of the SRSF2 protein and cause genome-wide splicing network alteration and aberrant maturation of different hnRNPs, including HNRNPA2B1, HNRNPM, HNRNPH1, and HNRNPH3, especially in myelodysplastic syndromes." (PMID 32596243, 2020). "Mutations in LUC7L2, PRPF8,SF3B1, SRSF2, U2AF1, and ZRSR2 genes occur at various frequencies ranging between 40% and 85% in different subtypes of myelodysplastic syndrome (MDS) and 5% and 10% of acute myeloid leukemia (AML) and myeloproliferative neoplasms (MPNs)." (PMID 31766606, 2019). "Studies revealed that there are also mRNA splicing events, particularly in SF3B1, U2AF1, and SRSF2, in hematological tumors such as chronic lymphocytic leukemia (CLL) and myelodysplastic syndrome (MDS)." (PMID 31798590, 2019). "Mouse genetics has revealed that mutagenesis of SRSF2 and SF3B1 drives myelodysplastic syndromes characterized by leukopenia, macrocytic anemia, myeloid, and erythroid dysplasia." (PMID 29875770, 2018). "SRSF2 mutations occur in up to 25% of acute myeloid leukemia (AML) and 17% of myelodysplastic syndrome (MDS) cases and are associated with poor prognosis, yet no mutation-directed therapy exists." (PMID 41279606, 2025). "Although mutations in SRSF2 are frequently observed in individuals with myelodysplastic syndromes (MDS) or chronic myelomonocytic leukemia (CMML), SRSF2 has not been commonly associated with human neurodegenerative disease." (PMID 34673031, 2021). "Notably, the critical role of mutations in epigenetic regulators and splicing factors, such as ASXL1, SRSF2 and U2AF1, in impaired hematopoiesis and the development of myelodysplastic syndromes (MDS), was validated in preclinical and clinical studies." (PMID 37444441, 2023). "Various splicing factors, including SRSF2, could be inhibited by telomere dysfunction, leading to altered differentiation in common myeloid progenitor (CMP) and development of classic myelodysplastic syndrome (MDS) phenotype." (PMID 39034387, 2024). "SRSF2 mutation has been frequently reported in myelodysplastic syndromes (MDS) and CMML patients which is related to shorter OS and may be considered as an adverse prognostic risk factor in MDS, but not in CMML, however, which was undetermined in CNL." (PMID 33822276, 2021).